ANXA6 (annexin A6)
Diseases named in the same sentence as ANXA6 in open-access papers (continued):
Sharing a sentence is not in itself a finding about the gene and the disease.
prostate carcinoma (3 papers, 2023). A carcinoma that arises from epithelial cells of the prostate gland. "The data presented here suggest a potential role for CAFs to upregulate ANXA6 expression in early disease stages in prostate cancer, which promotes increased epithelial cell proliferation, suggesting the possibility of therapeutic targeting of this CAF-specific signalling mechanism." (PMID 36765657, 2023).
thyroid cancer (3 papers, 2020 to 2023). "This includes studies identifying that exposure of female mice to the suspected endocrine-disrupting xenobiotic plastic precursor bisphenol A, led to AnxA6 upregulation and that this may potentially contribute to the etiology of thyroid cancer in women." (PMID 32784650, 2020).
adenoma (2 papers, 2020 to 2023). A neoplasm arising from the epithelium. "Elevated ANXA6 was detected in the feces of colorectal cancer patients, implicating ANXA6 as a fecal biomarker for early detection of high-risk adenomas and colorectal cancer." (PMID 37129645, 2023). "A protein panel, consisting of haptoglobin (Hp), LAMP1, SYNE2, and ANXA6, was identified for the detection of high‐risk adenomas (sensitivity of 53% at specificity of 95%)." (PMID 31784980, 2020). "We conclude that Hp, LAMP1, SYNE2, LRG1, RBP4, FN1, and ANXA6 may be of value as stool biomarkers for early detection of high‐risk adenomas and CRCs." (PMID 31784980, 2020). "Next to Hp, LAMP1, SYNE2, and ANXA6 were selected in the analysis for high‐risk adenomas, and also LRG1, RBP4, and FN1 for the high‐risk adenomas and CRCs." (PMID 31784980, 2020). "We identified a biomarker panel of Hp, LAMP1, SYNE2, and ANXA6 for identification of high‐risk adenomas and two biomarker panels – Hp and LRG1, as well as Hp, LRG1, RBP4, and FN1 – for identification of high‐risk adenomas and CRCs that outperformed hemoglobin." (PMID 31784980, 2020).
Alzheimer disease (2 papers, 2023 to 2025). A progressive, neurodegenerative disease characterized by loss of function and death of nerve cells in several areas of the brain leading to loss of cognitive function such as memory and language. "Furthermore, it has been demonstrated that, in conjunction with annexin A2, annexin A6 interacts with tau, which is thought to contribute to the pathological redistribution of tau in Alzheimer’s disease." (PMID 37108598, 2023).
aortic valve disease (2 papers, 2021 to 2022). "An in vitro study demonstrated EVs secretion with elevated calcium and Annexin A6 from rat VICs cultured with high calcium and phosphate and suggested a role in calcified aortic valve disease evidenced by co-localization of Annexin A6 with EVs in the aortic valve." (PMID 35155428, 2022).
bladder urothelial carcinoma (2 papers, 2020). "We found that ANXA6 may play the same role in bladder urothelial carcinoma." (PMID 32420368, 2020).
cervical tumor (2 papers, 2011 to 2020). "Knockdown of ANXA6 decreased autophagy levels and increased cervical tumor growth, while induction of autophagy significantly suppressed cervical tumorigenesis." (PMID 33135350, 2020).
colorectal cancer (2 papers, 2023 to 2025). A primary or metastatic malignant neoplasm that affects the colon or rectum. "ANXA6 protein has also been reported to be enriched in fecal samples from patients with colorectal cancer." (PMID 41522448, 2025).
Depression (2 papers, 2022 to 2024). "Third, we only detected MANF/EWSR1/ANXA6 pathway in serum, future studies should directly detect the levels of these molecules in the central nervous system, such as cerebrospinal fluid, to further pinpoint the role of this pathway in depression." (PMID 36585419, 2022). "Meanwhile, MANF, EWSR1, and ANXA6 were significantly correlated to TC concentrations and depression severity, and they could be potential biomarkers for diagnosing MDD." (PMID 36585419, 2022). "Moreover, based on the IPA database analysis, we hypothesized that MANF/EWSR1/ANXA6 pathway might act as a bridge between low serum lipids and depression." (PMID 36585419, 2022). "In major depressive disorder, the MANF/EWSR1/ANXA6 pathway has been suggested as a potential link between hypolipidemia and major depression." (PMID 39722850, 2024). "The results showed that compared to HCs, MDD patients had a significantly lower level of MANF and higher levels of ANXA6 and EWSR1, and these molecules were significantly correlated with both TC level and Hamilton Depression Rating Scales (HDRS) score." (PMID 36585419, 2022). "Meanwhile, both EWSR1 and ANXA6 were found to be significantly increased in MDD patients, and significantly correlated to depression severity (positively) and TC level (negatively)." (PMID 36585419, 2022). "Besides, MANF, EWSR1, and ANXA6 were found to be significantly altered in the serum of MDD patients and correlated with serum lipid and the severity of depression symptoms." (PMID 36585419, 2022).
dyslipidemia (2 papers, 2018 to 2022). "Prolonged HFD feeding induces dyslipidemia and we next compared lipid levels and lipoprotein profiles in the plasma of WT and AnxA6-KO mice." (PMID 30110341, 2018). "Thus, the effect of antidepressants in improving dyslipidemia may be mediated by the MANF/EWSR1/ANXA6 pathway, which is worthy to be investigated in the future." (PMID 36585419, 2022).
Fibroadenoma (2 papers, 2020). A benign tumor of the breast characterized by the presence of stromal and epithelial elements. "For fibroadenoma tissues, compared with both fibroadenoma-adjacent and normal tissues, there were six up-regulated (ANXA6, VCP, SERPINH1, galactosidase alpha, NNT, and MMP11) and 38 down-regulated (KRT10, KRT1, ALDH1A1, ECM1, and others) proteins in fibroadenoma." (PMID 33194682, 2020).
heart failure (2 papers, 2015 to 2022). Inability of the heart to pump blood at an adequate rate to meet tissue metabolic requirements. "In a porcine hypertension and left ventricle hypertrophy model of heart failure, annexin A6 protein levels were upregulated in the failing heart, with annexin A6 localizing to the sarcolemma." (PMID 35866481, 2022). "As mitochondrial dynamics is emerging as a potential new therapeutic target for heart failure, the scaffolding activity offered by Anxa6 holds much promise as a positive regulator of mitochondrial dynamics in hypertrophied cardiomyocytes." (PMID 26335715, 2015).
Hypertension (2 papers, 2022). The presence of chronic increased pressure in the systemic arterial system. "Furthermore, univariate analysis showed that age (p = 0.001), age at disease onset (p = 0.003), arthritis (p = 0.014), weight (p = 0.000), BMI (p = 0.000), hypertension (p = 0.002), and the rs11960458 SNP in AnxA6 (p = 0.014) were significantly associated with ApoB levels." (PMID 36498634, 2022). "Moreover, multiple regression analysis demonstrated that the rs11960458 SNP of AnxA6 was significantly associated with the levels of TC, LDL, and ApoB after adjusting for age, gender, age at disease onset, weight, BMI, arthritis, diabetes, and hypertension." (PMID 36498634, 2022).
invasive breast carcinoma (2 papers, 2013 to 2022). A carcinoma that infiltrates the breast parenchyma. "Lastly, protein expression of the ANXA6 gene (mutated only in two patients with a CR) is required for membrane localization of activated EGFR and persistent activation of MAP kinaseERK1/2 and PI3K/Akt pathways in invasive breast cancer cells." (PMID 34791836, 2022). "In this study, we investigated the contribution of AnxA6 in the activity of EGFR in invasive breast cancer cells and examined whether the expression status of AnxA6 influences the response of these cells to EGFR-targeted tyrosine kinase inhibitors (TKIs) and/or patient survival." (PMID 24354805, 2013). "Given that down regulation of AnxA6 in invasive breast cancer cells was accompanied by a decrease in the total and activated EGFR in invasive breast cancer cells, we speculated that AnxA6-depletion in these cells might affect their response to EGFR-targeted TKIs." (PMID 24354805, 2013).
liver cancer (2 papers, 2021 to 2024). An epithelial or non-epithelial malignant neoplasm that arises from the liver. "Compared with mouse normal liver tissues, the IHC staining revealed that the levels of SENP1 and RHOU were a relatively high expression in mouse liver cancer tissues, but AnxA6 was decreased." (PMID 38566133, 2024). "It has been reported that the specificity of ANXA6 is decreased in the context of human HCC, indicating its function in the development of liver cancer." (PMID 33505467, 2021).
lung carcinoma (2 papers, 2019). "Another study also reported that lapatinib, an anti-cancer drug developed by GlaxoSmithKline (GSK), which is used as a treatment for solid tumors such as breast and lung cancer was found to induce ANXA6 expression." (PMID 31877708, 2019).
metastatic diseases (2 papers, 2020 to 2025). "On the other hand, we suggest that drug combinations targeting ANXA3/ANXA6, and ANXA11/ANXA7 might be useful against lung- and liver-metastatic diseases, respectively." (PMID 40410902, 2025). "Since the expression levels of AnxA6 increased with disease progression, we next evaluated whether AnxA6 expression levels detected by IHC differed between TNBC (n = 15) and non-TNBC (n = 116) malignant/metastatic tumors." (PMID 32298357, 2020).
myeloma (2 papers, 2023 to 2024). "Despite its inclusion in MISEV guidelines, ANXA6 may be unsuitable as a small EV marker for myeloma cells under our experimental conditions." (PMID 39126063, 2024). "This suggests that either the isolation methods employed in this study exclude vesicles containing ANXA6, or that these myeloma cells do not produce ANXA6-containing EVs." (PMID 39126063, 2024). "Although we were able to detect ANXA6 in myeloma cell lysates, no signal was observed in EV samples from both isolation techniques." (PMID 39126063, 2024).
neuroblastoma (2 papers, 2022). Neuroblastoma (NB) is the most common solid, extracranial childhood tumor. "Plasmid overexpression of annexin A6 showed that annexin A6 localizes to the plasma membrane of injured neuroblastoma cells in culture, further suggesting that the mechanisms regulating muscle membrane repair may also occur in the brain." (PMID 35866481, 2022). "It has been observed that the ionomycin treatment of murine neuroblastoma cells results in translocation to the cell membrane of ANX, in the following order: ANXA2, ANXA4, ANXA6, ANXA1, ANXA5." (PMID 35207075, 2022).
squamous carcinoma (2 papers, 1995 to 2023). "This is associated with reduced growth in squamous cell carcinomas with elevated ANXA6 as well as decreased wound healing, stroma and organ-type stroma invasiveness." (PMID 37129645, 2023).
viral infection (2 papers, 2020 to 2025). "Studies have shown that ANXA6 is associated with cell proliferation, survival, differentiation, inflammation, membrane repair, and viral infection 13-19." (PMID 40959268, 2025). "ANXA6 was reported to interact with Influenza A virus M2 protein to impair the virus infection." (PMID 33425920, 2020).
abdominal aortic aneurysm (1 paper, 2023). Enlargement and ballooning of the vessel that supplies arterial blood to the abdomen, pelvis and legs. "EZH2 regulates ANXA6 promoter H3K27me3 modification, inhibits ANXA6 expression, attenuates Ang II-induced senescence in blood smooth muscle cells, and inhibits the progression of an abdominal aortic aneurysm (AMA)." (PMID 37129645, 2023).
abortion (1 paper, 2025). the ending of pregnancy by removing a fetus or embryo before it can survive outside the uterus. "Further studies revealed that overexpression of ANXA6 in normal pregnant mice resulted in increased embryo reabsorption, whereas knockdown of ANXA6 in abortion-prone mice alleviated embryo reabsorption." (PMID 40959268, 2025). "Further studies revealed that overexpression of ANXA6 in normal pregnant mice resulted in increased embryonic resorption, whereas knockdown of ANXA6 in abortion-prone mice alleviated embryonic resorption." (PMID 40959268, 2025). "Finally, in an abortion mouse model, the ANXA6 expression level in decidual tissues was notably increased and highly correlated with pyroptosis." (PMID 40959268, 2025).
amyloid (1 paper, 2025). "In this work, we have demonstrated a role of annexin A6 in reducing DNs in the 5XFAD amyloid mouse model." (PMID 40411591, 2025). "Future work will also focus on testing the ability of overexpressed and exogenous annexin A6 to decrease DNs and prevent in amyloid mouse models the seeding and spreading of pathologic tau isolated from human AD brain." (PMID 40411591, 2025). "Overexpression of annexin A6 in brains of 5XFAD mice decreased size and quantity of dystrophic neurites and accumulation of phospho-tau181, an early biomarker of amyloid pathology." (PMID 40411591, 2025). "We show that the membrane repair protein annexin A6 is expressed in neurons of human and murine brains, and overexpression of annexin A6 in the 5XFAD amyloid mouse model reduces DNs and p-tau181, while dominant-negative annexin A6 increases DNs and p-tau181." (PMID 40411591, 2025).
asthma (1 paper, 2020). "Furthermore, the hapten challenge of a nonatopic asthma mouse model sensitive to the organofluorine dinitrofluorobenzene also led to increased AnxA6 levels." (PMID 32784650, 2020).
bladder tumors (1 paper, 2021). "ANXA2, ANXA3, ANXA4, ANXA8, and ANXA9 were significantly increased in bladder tumor tissues, while ANXA6, ANXA7, and ANXA11 were significantly decreased." (PMID 34484309, 2021).
brain infarction (1 paper, 2025). Tissue necrosis in any area of the brain, including the cerebral hemispheres, the cerebellum, and the brain stem. "Further tests showed that administration of AnxA2, AnxA5, AnxA6, or AnxA7 to the healthy mouse brain caused brain CaP deposition, as tested by the Alizarin Red S assay, in association with brain infarction, as detected by the TTC assay." (PMID 39820937, 2025).
breast disease (1 paper, 2020). "We also analyzed the expression of AnxA6, GRF2, SOS1 and Ki67 by immunohistochemistry (IHC) in a breast disease spectrum and following chemotherapy." (PMID 32298357, 2020).
cerebellar degeneration (1 paper, 2021). Degeneration of the cerebellum. "Strikingly, lack of AnxA6 in NPC1-deficient animals (Npc1−/−/Anxa6−/−) did not prevent cerebellar degeneration." (PMID 33810523, 2021).
chondrosarcoma (1 paper, 2025). A malignant cartilaginous matrix-producing mesenchymal neoplasm arising from the bone and soft tissue. "Annexin-A6 (ANXA6) transcripts were also downregulated in R132Q-expressing HT1080∗ xenografts compared to both R132H and WT chondrosarcoma models." (PMID 40188944, 2025).
diabetes (1 paper, 2022). "In addition, our results demonstrated that BMI and diabetes were positively correlated with the increased levels of ApoB and LDL, respectively, which may be due to the fact that AnxA6 stimulates endocytosis and is involved in the trafficking of LDL to the pre-lysosomal compartment." (PMID 36498634, 2022).
fatty liver disease (1 paper, 2018). A reversible condition wherein large vacuoles of triglyceride fat accumulate in liver cells via the process of steatosis. "Together with increased AnxA6 levels in white adipose tissue from obese mice, this suggested AnxA6 levels to influence fatty acid release from adipocytes, a critical risk factor for the development of fatty liver disease." (PMID 30110341, 2018).
Hepatic fibrosis (1 paper, 2023). The presence of excessive fibrous connective tissue in the liver. "Not only that, ANXA2 may also promote hepatic stellate cell activation and collagen fibril synthesis by participating in the Anxa6/miR-9-5p/Anxa2 pathway or increasing the expression of osteopontin, thus leading to the onset and acceleration of hepatic fibrosis." (PMID 38192427, 2023).
Hyperglycemia (1 paper, 2018). An increased concentration of glucose in the blood. "However, AnxA6-deficient mice failed to effectively lower blood glucose levels at later time points (60–180 min), and continued to exhibit hyperglycemia." (PMID 30110341, 2018). "Taken together, the hyperglycemia observed in the PPT of HFD-fed AnxA6-KO mice was not due to impaired insulin signaling or altered activity of insulin-sensitive transcription factors modulating genes responsible for glycemic control during the PTT." (PMID 30110341, 2018).
hyperlipidemia (1 paper, 2018). "In line with prolonged HFD feeding inducing hyperlipidemia, total plasma triglycerides and cholesterol were elevated in both WT and AnxA6-KO strains." (PMID 30110341, 2018).
idiopathic dilated cardiomyopathy (1 paper, 2022). Decreased function of the heart associated with cardiac enlargement and congestive heart failure, of unknown cause. "In a study of human idiopathic dilated cardiomyopathy (DCM), left ventricle samples showed a 1.2-fold increase in annexin A6 protein expression in failing hearts (n = 11) compared with nonfailing hearts (n = 9), with annexin A6 localization at the sarcolemma and transverse tubules." (PMID 35866481, 2022).
infarction (1 paper, 2024). A localised pathological necrosis of tissue resulting from obstruction of the blood supply usually by a thrombus, an embolus, or vascular torsion. "We overexpressed and down‐regulated brain ANXA6 and evaluated infarction volume, neurological function, and synaptic plasticity‐related proteins post I/R." (PMID 38380783, 2024). "ANXA6 overexpression significantly decreased the modified neurological severity score (p = 0.0109) 1 day post I/R and the infarction area at 1 day (p = 0.0008) and 7 day (p = 0.0013) post I/R, and vice versa." (PMID 38380783, 2024). "ANXA6 OE significantly decreased the infarction area compared to the EV group at 1 day (p = 0.0008) and 7 days (p = 0.0013) post I/R." (PMID 38380783, 2024). "Additionally, plasma ANXA6 levels positively correlated with infarction volume and NIHSS scores." (PMID 38380783, 2024).
influenza (1 paper, 2024). An acute viral infection of the respiratory tract, occurring in isolated cases, in epidemics, or in pandemics; it is caused by serologically different strains of viruses (influenzaviruses) designated A, B, and C, has a 3-day incubation period, and usually lasts for 3 to 10 days. "The barrier may be related to host restriction factors that prevent influenza development, such as the protein AnxA6 that inhibits the packing of influenza virion." (PMID 38211734, 2024).
intestinal infection (1 paper, 2025). "To further investigate the role of ANXA6 during O157:H7 intestinal infection, we exposed mice to O157:H7 wild-type (WT), espF-deficient (ΔespF), and espF-complemented (p-ΔespF) strains." (PMID 41522448, 2025).
ischemic stroke (1 paper, 2025). A stroke disorder caused by obstruction of blood flow to the brain, due to thrombotic (local blood clot formation) or embolic (due to a blood clot or other material traveling from another site) event. "This investigation demonstrated that the neuron-expressed, plasma membrane-associated Ca2+-binding proteins annexin (Anx) A2, AnxA5, AnxA6, and AnxA7 contributed to neuronal CaP deposition in the mouse model of ischemic stroke." (PMID 39820937, 2025). "This investigation demonstrated that several neuron-expressed annexins, including annexin (Anx) A2, AnxA5, AnxA6, and AnxA7, play a role in the development of acute neuronal CaP formation and deposition in the mouse model of ischemic stroke." (PMID 39820937, 2025). "Ischemic stroke did not cause a substantial change in the relative expression of AnxA2, AnxA5, AnxA6, and AnxA7 in the cortical neurons in reference to sham controls." (PMID 39820937, 2025).
kidney tumour (1 paper, 2022). "Moreover, ANXA6 displayed the highest incidence rate of genetic variations among the super family members, which might be related to kidney tumour progression." (PMID 39290334, 2022).